PRR23D2 (proline rich 23 domain containing 2)
Tractability: No criterion of Open Targets' tractability assessment is met for any kind of drug.
Gene: Protein-coding gene on chromosome 8 (7,778,591 to 7,781,413, reverse strand). Ensembl gene ENSG00000255378.
Homologues: Paralogues in human: PRR23D1 (100% identical), PRR23C (25% identical), PRR23B (25% identical), PRR23A (25% identical), PRR23E (12% identical).